FTO (FTO alpha-ketoglutarate dependent dioxygenase)
Diseases named in the same sentence as FTO in open-access papers (continued):
Sharing a sentence is not in itself a finding about the gene and the disease.
Obesity (continued). "Sensitivity analyses showed that these diet effect modifications on HbA1c were similar to a GRS that also included SNPs in FTO and after controlling for obesity markers." (PMID 31592155, 2019). "The FTO also known as alkB homolog 9 (ALKBH9), which is a member of the Alkb protein family and associated with obesity." (PMID 31452869, 2019). "Moreover, people with the risk allele at FTO may be more vulnerable to diet-related obesity." (PMID 31126299, 2019). "In human obesity, IRX3 is a target of the FTO risk loci with allele carriers having increased IRX3 expression in early adipogenesis where it is proposed to regulate adipocyte function and browning through the modulation of mitochondrial genes." (PMID 31086124, 2019). "Given the strong role of the FTO locus in obesity, FTO was considered as a suitable candidate to establish the genetic link between obesity-related traits and vitamin B12 concentrations." (PMID 31516636, 2019). "Because the intron lacks protein-altering variants and the biological pathways involved are not well-known, several studies have provided a candidate mechanism of obesity and FTO." (PMID 31075924, 2019). "In mouse models, inactivation of the FTO gene results in lean phenotype, whereas overexpression of FTO leads to increased food intake and obesity." (PMID 29321599, 2018). "The top predictors, rs10521308 (FTO), rs2206135 (CTNNBL1), cg13438334 (DGAT1), and cg22390041 (ALDH4A1) are located in genes known to be associated with obesity risk." (PMID 30255820, 2018). "A study performed on newborns in Greece assessed both risk FTO and MC4R variants and concluded that approximately 80% of the Greek population are genetically predisposed to obesity development further on in life." (PMID 30338250, 2018). "Variations in the FTO intron 1, which affect primary transcript levels, have been widely related to obesity and obesity-related traits." (PMID 29410390, 2018). "Studies in mice suggest a link between FTO, obesity and metabolic syndrome by driving obesity-prone behaviors." (PMID 30319972, 2018). "Additional studies are needed to fully understand the effect of obesity/diabetes on hepatic FTO expression." (PMID 30388740, 2018). "Conversely, overexpression of FTO in mice develops obesity by increased food intake, demonstrating the pivotal role of FTO expression itself in obesity." (PMID 30105001, 2018). "Genome-wide association studies of obesity in humans have isolated the FTO/IRX3 locus, where it appears that a variant in an intron of the FTO gene affects body mass index by a regulatory effect on the neighbouring gene IRX3." (PMID 29361907, 2018). "Notably, of 104 GO functional categories, two GO terms “glucose homeostasis” and “response to glucose” were also enriched by T2D GWAS genes (such as TCF7L2 and FTO), indicating that obesity associated genes might confer T2D risk through its primary effect on adiposity." (PMID 29966015, 2018). "Further functional studies are needed to determine the precise role of the FTO gene in determining obesity and its complications." (PMID 30338250, 2018). "The aim of this study was to investigate the association of candidate gene single nucleotide polymorphisms (SNPs), namely FTO (rs9939609) and VDR (rs1544410), with obesity in the UAE population." (PMID 29343214, 2018). "The role of polymorphisms of several genes (e.g. FTO, PRAR, adrenergic beta receptor, and Perilipin in obesity has been frequently discussed." (PMID 29677190, 2018). "We did not detect statistical associations between LEPR rs11371101, FTO rs9939609, MC4R rs2229616, and PPARG-2 rs1801282 polymorphisms and most obesity-related phenotypes and metabolic parameters." (PMID 29679223, 2018). "In 2018, a case control study conducted on obese Iranian women showed that several FTO variants including rs9939609 were associated with T2DM and obesity as well." (PMID 30170548, 2018).
Obesity (continued). "Further subgroup analyses were performed for Caucasians, East Asians, and South Asians to determine the relationship between protein intake, FTO genotype, and measures of obesity." (PMID 29484031, 2018). "It is proposed that abnormal activity of hepatic signaling pathways involving FTO links metabolic impairments such as obesity, type 2 diabetes and nonalcoholic fatty liver disease (NAFLD)." (PMID 30388740, 2018). "On the other hand, several studies revealed a strong association between different variants within the FTO gene and BMI or diabetes supporting that the impact of FTO on obesity or diabetes is population-dependent." (PMID 30170548, 2018). "Several studies have elucidated the effects of environment and FTO variant on obesity, evident in the well-studied time spent sitting (TSS), physical activity (PA), and dietary correlates of obesity." (PMID 28607773, 2017). "Although the link between the FTO polymorphism and BMI has been confirmed in multiple studies, how expression of FTO leads to obesity is not well understood." (PMID 28533023, 2017). "Previous studies which concerned about different populations, reported that increased BMI heritability has sex-based differences and obesity trait is mediated through FTO and occurs independently in both sexes." (PMID 28662178, 2017). "In the current study, we explored the association of FTO rs17817449 (G>T), GNB3 rs5443 (C825T) and MCR4 (A822G) genes SNP with obesity and obesity-related metabolic traits in a small sample of Saudi population." (PMID 29937877, 2017). "Our results indicate that high physical activity diminishes the obesity-promoting effect of FTO and MC4R." (PMID 28384342, 2017). "We suspect these epigenetic FTO interactions with the FTO gene will have modifiable effects on obesity and telomere attrition." (PMID 28859657, 2017). "Previous studies on FTO gene-diet interaction have focused more on FTO rs9939609 and its interaction with macro-nutrients in relation to obesity." (PMID 28954439, 2017). "In conclusion, the present data from an all-adult population survey demonstrate that age and gender importantly modify interactions between lifestyle factors and the obesity-promoting effects of FTO and MCR4." (PMID 28384342, 2017). "In summary, in our sample of Chinese children, we replicated eight adult East Asian obesity-related loci (in/near FTO, MC4R, GNPDA2, PCSK1, SEC16B, MAP2K5, ITIH4 and BDNF) in the same direction of effect as previous reports in adults." (PMID 29212175, 2017). "In this report we demonstrate, for the first time, the favorable effects of RAS supplementation on body weight, gene expression, and promoter methylation of the FTO gene in mice with HFD obesity." (PMID 29098158, 2017). "Examinations of many patient populations have shown certain correlations between increased BMI, obesity and the presence of several SNPs, most notably rs9939609 in intron 1 of the FTO gene (OR = 1.42 in individuals with European ethnicity)." (PMID 28717589, 2017). "In this pilot study, we analyzed SNP rs9939609 of the FTO gene in a group of people with obesity and control in Nigeria." (PMID 28607773, 2017). "The AA genotype proportion of the FTO rs9939609 reported in this study was significantly higher in people with obesity when compared with control (25.2% to 10.2%); this is in agreement with earlier studies." (PMID 28607773, 2017). "In other words, the over-all effect of FTO on obesity was negligible in highly active individuals aged between 20 and 40 years." (PMID 28384342, 2017). "In another report, the FTO gene was a higher risk factor for obesity, especially in Portuguese subjects with class III obesity." (PMID 29317790, 2017). "A large-scale meta-analysis of the FTO obesity locus in 218,166 adults showed that being physically active attenuates the BMI-increasing effect of this locus by ~30%." (PMID 28448500, 2017).
Obesity (continued). "Obtained results revealed that FTO SNPs rs1558902, rs1421085, rs12149832, rs9930506, rs9939609 had the strongest influence on obesity phenotype in our study group which is consistent with other studies." (PMID 28662178, 2017). "Presented case-control analysis comprising men and women subgroups gave a novel point of view on genetic association of FTO and IRXB cluster with obesity and overweight which depend on sex and age." (PMID 28662178, 2017). "The aim of this study was to evaluate the association of the FTO rs17817449 (G>T), GNB3 rs5443 (C825T) and MC4R Asn274Ser (A822G) gene polymorphism with obesity and obesity-related metabolic traits in Saudi subjects." (PMID 29937877, 2017). "This is the first study to examine a possible FTO–dietary fiber interaction in relation to obesity phenotypes in a Middle-Eastern population." (PMID 29273742, 2017). "Subcutaneous and visceral adipose tissue biopsies from 22 class III obesity patients were analyzed for FTO and ABCA1 mRNA expression." (PMID 28464932, 2017). "Dietary fiber intakes modified the association of FTO SNPs and the GRS with general obesity, an effect which was more pronounced in those who consumed high levels of dietary fiber and had a high number of risk alleles." (PMID 29273742, 2017). "Our study showed significant interaction between FTO variants and MDS in relation to obesity phenotypes." (PMID 28954439, 2017). "Subsequent to the fat mass and obesity associated (FTO) gene, the melanocortin 4 receptor (MC4R) gene was the second gene validated by the genome-wide association study (GWAS) for obesity." (PMID 28520814, 2017). "In particular, FTO and FABP2 gene polymorphisms were significantly associated with susceptibility to MS and obesity in this cohort." (PMID 28738793, 2017). "Further studies will be required to confirm that the FTO gene has an effect on the dietary factors to promote weight gain for obesity." (PMID 28924523, 2017). "Actually, FTO rs9939609 SNP is considered one of the most important gene variants predisposing to obesity and the LIPGENE-SU.VI MAX study showed that FTO rs9939609 is also associated with overweight and abdominally obesity." (PMID 27894098, 2017). "Full role of FTO first intron rs9939609 on obesity etiology and their role in energy expenditure need more to be done." (PMID 28607773, 2017). "FTO overexpression in mice led to a dose-dependent increase in body and fat mass, and increased food intake resulting in obesity." (PMID 28933365, 2017). "This association was replicated in several distinct ethnic populations, making FTO the single strongest genetic factor of obesity." (PMID 28615046, 2017). "The first study involving this FTO SNPs and obesity was performed in an English diabetic population; where the SNP most strongly associated with an increased BMI was rs9939609." (PMID 26726774, 2016). "The aim of this study is to assess the use of selected flavonoids as potential obesity preventing agents targeting the three dimensional structure of FTO protein followed by an in vitro validation." (PMID 27454254, 2016). "We identified obesity association for 6 SNPs near SEC16B, RBJ, CDKAL1, TFAP2B, MAP2K5 and FTO (odds ratios (ORs) ranged from 1.19 to 1.41, nominal two-sided P-values < 0.05)." (PMID 26800887, 2016). "FTO rs1421085, CDKAL1 rs2206734, TNNl3K rs1514176, GIPR rs11671664 and the GRS were associated with obesity measures at baseline and/or follow-up." (PMID 26727462, 2016). "The major lipid storage genes are those for the peroxisome proliferator-activated receptor γ (PPARG 3p25) mainly found in adipose tissue, and furthermore the obesity-related FTO (16q12.2)." (PMID 27147943, 2016). "The combined role of FTO and physical activity in obesity and adipocyte browning, in conjunction with epigenetic mechanisms, strengthen the biological rationale and confidence in the statistical interaction." (PMID 26727462, 2016).
Obesity (continued). "Our findings suggest that the effect of the FTO SNPs, rs8050136 and rs11076023, on obesity is influenced by high carbohydrate and dietary fibre intakes and low physical activity levels." (PMID 27274759, 2016). "Given its role in T2D and obesity, FTO was considered as a candidate for our gene-diet/-physical activity interaction study." (PMID 27274759, 2016). "Only a very small number of above-threshold GWAS loci, including SORT1 for LDL cholesterol, the FTO/IRX3 locus for obesity, and the SCN5A/SCN10A locus for QRS duration, have been investigated in detail." (PMID 27162171, 2016). "Westudied a possible association of polymorphisms FTO rs9939609,PPARG rs1801282, and ADIPOQ rs4632532 andrs182052 with obesity phenotypes in 215 Mexican children." (PMID 27560839, 2016). "The strongest reported SNP associations for BMI are provided by rs1558902 (FTO) and rs13021737 (TMEM18), which have a well-established impact on obesity." (PMID 27336604, 2016). "In order to increase our understanding of the contributions of this region of FTO to the development of obesity in the Mexican population, we performed a case-control study in a population that included normal-weight, overweight, and obese patients." (PMID 26726774, 2016). "To illustrate the application of the relationship described in Equation to experimental data, we used GWAS data around the well-established obesity locus, FTO, generated by a recent large study of extreme BMI." (PMID 28018425, 2016). "Obesity-associated cis-acting elements in non-coding region of FTO regulate the expression of IRX3 gene, thus activating obesity networks." (PMID 27390851, 2016). "A few reports have shown a sex-specific effect of FTO variants on conferring susceptibility to obesity/adiposity, and some reports suggest that differences in the fat distribution and/or physical activity between men and women might affect the effects of FTO variants on obesity/adiposity." (PMID 27820839, 2016). "Overall, and consistent with most previous studies, our results strongly indicate that FTO has a very close relationship with obesity and fat mass, more than with other metabolic traits." (PMID 26726774, 2016). "Our results provide further evidence for the role of obesity in inflammation and highlight the pleiotropic effects of the FTO locus on both chronic inflammation and lipid metabolism." (PMID 27286809, 2016). "We however chose the FTO gene given the strength of the evidence linking FTO rs9939609 to obesity in both children and adults and the large prevalence of individuals with risk alleles." (PMID 27196523, 2016). "Studies by inactivation or overexpression of FTO in mice suggested that FTO tended to promote obesity and metabolic syndrome by driving obesity-prone behaviours such as increased food intake, consistent with its highest expression level in the brain." (PMID 27249342, 2016). "Comparison of association of FTO rs9939609,PPARG2 rs1801282, and ADIPOQ rs4632532 andrs182052 with obesity in different populations." (PMID 27560839, 2016). "A meta-analysis found that fat mass and obesity related gene FTO plays a critical role in leading to MS32." (PMID 27901076, 2016). "Significant interaction between FTO and physical inactivity on obesity has been reported in several studies from Europe and Asia; however, there are no studies, to date, among Asian Indians living in India." (PMID 27274759, 2016). "The FTO locus also showed a similar pattern of deviation from additivity in case–control analyses of obesity (pDOMDEV = 0.001) and severe obesity (pDOMDEV = 0.003)." (PMID 26961502, 2016). "The common variants FTO rs9939609 and MC4R rs17782313 were genotyped and their relationship with obesity-related traits was evaluated." (PMID 26032905, 2015). "Established obesity loci including FTO affect the level and the rate of change in BMI at 8 years in children." (PMID 26691922, 2015).
Obesity (continued). "However, in light of previous studies that suggest genetic association to obesity at the FTO locus may be age-dependent and because of the lower, narrower age range in our male cohort (mean = 19.9), we examined the role of age in this age-diverse female cohort (range from 16 to 45)." (PMID 26642925, 2015). "Correlation between the FTO rs9939609 genotypes and clinical/ paraclinical parameters and obesity comorbidities." (PMID 25866584, 2015). "This required further studies of FTO in knockout and overexpression animal models to understand the mechanism in which FTO influences obesity." (PMID 25825681, 2015). "There is compelling evidence that obesity, T2DM, prostate and breast cancer, and neurodegenerative diseases are all associated with increased FTO expression." (PMID 26691922, 2015). "In the field of obesity, the first gene that proved to be correlated with the polygenic type was FTO." (PMID 25866584, 2015). "This female-specific FTO effect has also been reported previously related to obesity, insulin sensitivity and glucose levels in children." (PMID 26445370, 2015). "FTO belongs to the family of Fe2+ and 2-oxoglutarate (2OG) dependent AlkB dioxygenases and contributes to non-syndromic human obesity." (PMID 25452335, 2015). "As FTO was considered the “obesity-gene” in 2007 when the first GWAS papers were published, many research groups sought out to examine FTO's role in the regulation of body weight." (PMID 26788058, 2015). "When selecting the SNPs to test, we aimed at choosing the ones mapping within or in proximity of well documented obesity genes (as FTO and MC4R, for instance) and as representative of the obesity status (both in terms of BMI and waist circumference)." (PMID 25890290, 2015). "Obesity and T2DM-associated genetic variations of FTO are associated with increased primary transcript levels of FTO mRNA." (PMID 26691922, 2015). "As it has been proposed that IRX3 and RPGRIP1L are primarily responsible for the enhanced obesity associated with the obesity-related SNPs in FTO12, 13, we compared mRNA levels of FTO, IRX3 and RPGRIP1L in WT gWAT and MEFs." (PMID 25881961, 2015). "The potential programming effects of FTO in the developmental of obesity has recently been reviewed by Sebert and colleagues." (PMID 26402696, 2015). "The fat mass and obesity-related gene (FTO) was the first gene shown to play a role in common obesity." (PMID 25881961, 2015). "The role of FTO as an important contributor to polygenic obesity was confirmed in GWAS for type 2 diabetes, BMI, early onset obesity, and incidentally in a population stratification approach." (PMID 25825681, 2015). "SNPs (single nucleotide polymorphisms) on a chromosome 16 locus encompassing FTO, as well as IRX3, 5, 6, FTM and FTL are robustly associated with human obesity." (PMID 25242086, 2014). "Although FTO has emerged as a major obesity-related gene particularly in populations of European descent, results in Asian populations are inconclusive." (PMID 25251416, 2014). "Nevertheless, demethylase activity of FTO is most likely the activity being the target for an anti-obesity therapy." (PMID 25144618, 2014). "For individual SNPs, the effect of adjustment for BMI was most notable for rs9936385 in FTO, an established obesity locus." (PMID 24845081, 2014). "Obesity research which has led to discoveries of the links between specific genes such as FTO and obesity, microRNAs and the change in our understanding of adipose tissue, amongst others, has not only been highly interesting but at times shocking." (PMID 26217496, 2014). "In this study, we systematically assessed the obesity-related genetic variations in FTO in a population-based case-control study." (PMID 25251416, 2014). "While much is known about the epigenetic mutations contributing to obesity and T2DM, less is certain with the expression regulation of FTO gene." (PMID 24877091, 2014).